EGFR (epidermal growth factor receptor)
Diseases named in the same sentence as EGFR in open-access papers (continued):
Sharing a sentence is not in itself a finding about the gene and the disease.
ulcerative colitis (15 papers, 2008 to 2025). An inflammatory bowel disease involving the mucosal surface of the large intestine and rectum. "Overexpression of TGF-α in gastric epithelium, leading to increased EGFR signaling, and comorbidity with ulcerative colitis have been implicated." (PMID 41041446, 2025). "In conclusion, this case report describes a patient with osimertinib‐induced ulcerative colitis, successfully managed with mesalazine, suggesting a possible association between the EGFR inhibitor and ulcerative colitis exacerbation." (PMID 40641492, 2025). "It has been established that in ulcerative colitis, the expression level of EGFR is significantly elevated and EGFR is critically involved in the activation of PI3K and AKT." (PMID 40649400, 2025). "Epithelial regeneration is an important process for recovery in the intestinal mucosa of ulcerative colitis, and EGFR stimulation is known to promote epithelial regeneration in a mouse model." (PMID 40641492, 2025). "The molecular docking analysis revealed promising binding affinities of ten BRLE bioactive compounds against four key ulcerative colitis-related targets (EGFR, SRC, STAT3, and AKT1), with binding scores ranging from −6.5 to −9.1 kcal/mol." (PMID 41465478, 2025). "It has also been shown that activation of EGFR signalling and related cell behaviours repairs damage to intercellular tight junctions and improves ulcerative colitis in a dextran sulphate sodium‐induced ulcerative colitis model." (PMID 40641492, 2025). "REG4 (regenerated islet derived 4 gene), identified through high-throughput sequencing of ulcerative colitis cDNA library, binds to and kills inflammatory Escherichia coli by activating epidermal growth factor receptor (EGFR) /Akt/cAMP response elements." (PMID 38426148, 2024). "Network pharmacology has also found that GQD can reduce the degree of inflammation in ulcerative colitis by downregulating the EGFR/PI3K/AKT signaling pathway and inhibiting the release of proinflammatory cytokines." (PMID 35356743, 2022). "Osimertinib‐induced inhibition of EGFR in the intestinal tract may exacerbate latent ulcerative colitis, triggering its clinical manifestation." (PMID 40641492, 2025). "In contrast to EGFR blockade in cancer, the rectal application of EGF-containing enemas to ulcerative colitis patients induced mucosal healing in 10 out of 12 patients, highlighting the crucial role of the EGFR signaling cascade in intestinal epithelial regeneration." (PMID 34830971, 2021). "Therefore, FS may influence the onset and progression of ulcerative colitis through its interaction with the EGFR." (PMID 40649400, 2025). "Twenty-two compounds obtained from the secondary screening were molecularly docked with ulcerative colitis-related target proteins (IL-1R, TLR, EGFR, TGFR, and Wnt) using AutoDock Vina." (PMID 37322476, 2023). "Lucidenic acid A emerged as the most promising compound, demonstrating exceptional binding to SRC (−9.1 kcal/mol), EGFR (−8.3 kcal/mol), and AKT1 (−8.8 kcal/mol), suggesting a multi-target therapeutic approach advantageous for treating the complex pathophysiology of ulcerative colitis." (PMID 41465478, 2025). "Molecular docking studies were performed to evaluate the binding affinity and interaction profiles of ten bioactive compounds from BRLE against the four key protein targets (EGFR, SRC, STAT3, and AKT1) identified through network pharmacology analysis for ulcerative colitis treatment." (PMID 41465478, 2025). "SRC, EGFR, AKT1, and PIK3R1 were the targets of highest potential, and the PI3K/Akt and MAPK pathways may be essential for the treatment of ulcerative colitis by bisdemethoxycurcumin." (PMID 36615264, 2022). "The findings indicated that FS could modulate the progression of ulcerative colitis via multiple targets, with STAT3, EGFR, ESR1, PTGS2, NF-κB1 and JUN identified as the six key targets significantly involved in the pathogenesis and progression of ulcerative colitis." (PMID 40649400, 2025).
urothelial bladder cancer (15 papers, 1991 to 2025). "In this study we investigated VEGF, EGFR as well as PSMA as targets for the detection of LN metastases with urothelial carcinoma of the bladder in the diagnostic setting by immunohistochemistry." (PMID 36581931, 2022). "In GBM, TERTp mutations coexist with EGFR amplification, and in urothelial bladder carcinoma, they are associated with FGFR3 (Fibroblast Growth Factor Receptor 3) mutations." (PMID 32204305, 2020). "Significant association of EGFR overexpression with tumor grade, muscularis propria invasion and recurrence signifies its prognostic value; therefore EGFR can be used as a prognostic biomarker in Urothelial bladder carcinoma." (PMID 29879970, 2018). "Another research group reported EGFR expression in 55.4% of all patients with urothelial bladder cancer." (PMID 36581931, 2022). "Expression of EGFR is, like in our model system UM-UC-3, detected in urothelial carcinomas of the bladder." (PMID 28775339, 2017). "As an example, in bladder urothelial carcinoma, Epidermal Growth Factor Receptor (EGFR)-, K-RAS-, and RAF-dependent pathways were activated in 42%, 22%, and 38% of cases, but only three patients carried the EGFR mutation and no mutation in K-RAS or RAF was found." (PMID 32708716, 2020). "In urothelial bladder cancer (UBC), the prevalence of EGFR overexpression ranges from 25% to 50%, with a higher frequency observed in muscle-invasive bladder cancer (MIBC) compared to non-muscle-invasive bladder cancer (non-MIBC)." (PMID 40364160, 2025). "We compared our results to the available literature of expression of VEGF, EGFR and PSMA on urothelial carcinoma of the bladder." (PMID 36581931, 2022). "Prostasin, a GPI-anchored serine protease crucial for epithelial differentiation and epidermal growth factor receptor (EGFR) proteolysis, was shown to be downregulated in high-grade urothelial bladder cancer cell lines." (PMID 29207682, 2017). "In this study we investigated the expression of vascular endothelial growth factor (VEGF), epidermal growth factor receptor (EGFR) and prostate-specific membrane antigen (PSMA) to analyze their potency as targets for the detection of lymph node (LN) metastases of urothelial carcinoma of the bladder." (PMID 36581931, 2022). "EGFR and PSMA do not seem suitable as imaging targets for urothelial carcinoma of the bladder because of the low staining results of these antigens in the current study." (PMID 36581931, 2022).
atrial fibrillation (14 papers, 2021 to 2025). A disorder characterized by an electrocardiographic finding of a supraventricular arrhythmia characterized by the replacement of consistent P waves by rapid oscillations or fibrillatory waves that vary in size, shape and timing and are accompanied by an irregular ventricular response. "The PPI network analysis illustrated that the hub genes related to atrial fibrillation are EGFR, GNG2, and FPR2." (PMID 34938350, 2021). "EGFR was reported to be highly regulated in patients with atrial fibrillation." (PMID 39285385, 2024). "For example, the effect of ibrutinib on atrial fibrillation is caused by its off-target inhibition of CSK, while the skin toxicities of ibrutinib likely involve its inhibition of EGFR as the symptoms overlap with those caused by selective EGFR inhibitors." (PMID 34485307, 2021). "Compared to older-generation BTKis, its reduced off-target inhibition of Tec kinase in platelets and epidermal growth factor receptor (EGFR) appears to reduce the incidence of atrial fibrillation (AF), bleeding, rash, and diarrhea." (PMID 39659349, 2024). "The protein-protein interaction network revealed that EGFR, GNG2, and FPR2 were related to atrial fibrillation." (PMID 34938350, 2021). "And bioinformatics analysis of upregulated genes indicates that pathway endodermal cell differentiation and key genes EGFR, GNG2, and FPR2 are related to atrial fibrillation." (PMID 34938350, 2021). "However, it is a non-selective inhibitor and its off-target activities on other kinases including epidermal growth factor receptor (EGFR), SRC, and other Tec family kinases can result in side effects such as atrial fibrillation and bleeding." (PMID 36294458, 2022). "We could conclude that EGFR, GNG2, and FPR2 were the most closely related to patients with atrial fibrillation." (PMID 34938350, 2021). "Besides this on-target effect, ibrutinib deactivates several off-targets, e.g., EGFR, ErbB2, ITK, and TEC, which might contribute to the antitumor effect but, at the same time, result in adverse events, such as atrial fibrillation (AF) and bleeding." (PMID 37373521, 2023).
chronic lymphocytic leukemia (14 papers, 2013 to 2024). "In another retrospective cohort enrolling patients with CD19+ R/R NHL and chronic lymphocytic leukemia, a CAR construct containing a CD28 costimulatory domain and coexpressing truncated epidermal growth factor receptor was used to generate CD19CAR-T cells." (PMID 36176002, 2022).
epilepsy (14 papers, 2015 to 2026). A brain disorder characterized by episodes of abnormally increased neuronal discharge resulting in transient episodes of sensory or motor neurological dysfunction, or psychic dysfunction. "In a previous study, we have shown that DNA methylation regulated potential gene networks, pathophysiological pathways including PDGFR, EGFR, NTRK3(RTKs) as well as mTOR signaling and several other potential epilepsy-related genes associated with FCD type II." (PMID 33192309, 2020). "It is likely that the increased expression of EGFR in the brain in epilepsy in some studies may be related to the infiltration of immune cells into the brain." (PMID 38067243, 2023). "The occurrence of high correlation between EGFR mutations and seizure incidence may extend the significance of this study making EGFR more than a mere disease marker to disclose novel avenues in the pathophysiology of BMs and epilepsy." (PMID 37240478, 2023). "This difference in results on EGFR upregulation and downregulation in patients with epilepsy may be explained by the influence of immune cells infiltrated in the epileptic region." (PMID 38067243, 2023). "In this study we have identified DNA methylation-regulated potential gene networks, pathophysiological pathways including PDGFR, EGFR, NTRK3 (RTKs), and mTOR signalling in addition to several other potential epilepsy-related genes associated with FCD type II pathology." (PMID 30568293, 2018). "In addition, overexpression of EGFR has also been observed in cases of epilepsy." (PMID 38067243, 2023). "There have been reports that EGFR expression is upregulated in immune cells in epilepsy, but not in nerve cells." (PMID 38067243, 2023). "However, the effect of a decrease in EGFR in neurons and an increase in tumour and immune cells on the development of epilepsy is not clear." (PMID 38067243, 2023). "CNG of EGFR (HR =3.08, 95% CI =1.82-5.19, P <0.001), HER3 (HR =1.71, 95% CI =1.06-2.76, P =0.03) and HER4 (HR =1.76, 95% CI =1.08-2.87, P =0.02) was identified as independent predictors of poor patient survival with respect to ages, WHO grade, radiotherapy and epilepsy." (PMID 29190914, 2017).
gynecological cancers (14 papers, 2011 to 2025). "More importantly, overexpression of EGFR and ErbB2 has been associated with poor survival in gynecological cancer patients." (PMID 32754300, 2020). "Considering the high level of mutation/overexpression of EGFR in gynecological cancers, some therapeutics compounds targeting this family of oncogene have been tested in gynecological cancers." (PMID 28008141, 2017). "Ongoing studies explore potential targeted therapeutic options for gynecological cancers, including the targeting of epidermal growth factor receptor (EGFR), androgen receptor, poly ADP-ribose polymerase (PARP), and vascular endothelial growth factor (VEGF)." (PMID 40490498, 2025). "Another family of oncogenes to consider in gynecological cancers is the epidermal growth factor receptors EGFR (HER-1) and ErbB2 (HER-2), which are known for being cell-surface receptors tyrosine kinases being structurally similar." (PMID 28008141, 2017). "In this study, we used a panel of gynecological cancer cell lines, with different EGFR/HER2 status, that we have previously characterized." (PMID 22185378, 2011). "Interestingly, these trials demonstrated that inhibiting EGFR in gynecological cancers is well tolerated but the efficiency is low when used alone, thus necessitating a combination with another chemotherapeutic drug." (PMID 28008141, 2017). "Interestingly, it has been demonstrated that EGFR and ErbB2 overexpression, in association with the activation of PI3K and MAPK signaling pathways, increase resistance to cisplatin and paclitaxel in gynecological cancers." (PMID 28008141, 2017). "The present report is the first one to bring out preclinical studies showing matuzumab resistance in vitro in gynecological cancer cell lines and highlights that impaired EGFR down-regulation might be the possible biological mechanism responsible for its inefficacy." (PMID 22185378, 2011). "In gynecological cancer, YBX1 was shown to be an important player impacting AKT and the downstream genes such as EGFR, Snail, or E-cadherin." (PMID 33816248, 2021). "In gynecologic cancers, common genes regulated by prognosis-alternative miRNAs such as BCL2, EGFR, PDGFRA, and VEGFA were also demonstrated to be combinational targets for anti-cancer drugs." (PMID 32523951, 2020). "Matuzumab, differently from cetuximab, was not able to induce EGFR down-regulation, with persistent signaling and gynecological cancer cell proliferation." (PMID 22185378, 2011). "Matuzumab combined with chemoradiation did not induce cytotoxic effects on gynecological cancer cell lines in vitro, most likely due to impaired EGFR degradation." (PMID 22185378, 2011). "Even though the majority of gynecological cancers express EGFR, these tumors are not solely dependent upon EGFR activity." (PMID 22185378, 2011). "Both EGFR and ErbB2 receptors can activate various signaling pathways, including both the PI3K and MAPK (via RAS-RAF oncogenes) which provide survival signaling, cell growth to tumors and contribute to the overall acquisition of chemoresistance in gynecological cancers." (PMID 28008141, 2017).
intestinal tumor (14 papers, 2013 to 2024). "While EGFR signaling is strongly implicated in the development of intestinal tumors, it appears that loss of the fine-tuning effects of PACS-2 is also not sufficient to impede tumor development or progression." (PMID 29312533, 2017). "Berberine reduced cell proliferation and induced apoptosis, which are associated with inhibition of Wnt and EGFR signaling pathways in intestinal tumor of Apcmin/+ mice." (PMID 24279644, 2013). "Furthermore, we show that this local JH activity is important for damage response and is necessary for intestinal tumor growth driven by activating mutations in Wnt and EGFR/Ras pathways." (PMID 28916802, 2017). "Importantly, it has been shown that Apc deficiency is associated with increased EGFR activity in intestinal tumor of Apcmin/+ mice." (PMID 24279644, 2013). "In the frame of this manuscript, we were able to show that a reduced amount of protein in the ingested diet has a significant positive effect on EGFR-induced intestinal tumors." (PMID 34766923, 2021). "The APC-mediated initiation of intestinal tumorigenesis requires normal epidermal growth factor receptor (EGFR) activity for the establishment of intestinal tumors." (PMID 32756527, 2020). "It indicated a requirement of AREG for the DCA‐induced effects on EGFR‐Akt signalling pathway activation in intestinal tumour cells." (PMID 29956475, 2018). "We then investigated the effects of DCA on ADAM‐17/EGFR signalling axis in intestinal tumour development." (PMID 29956475, 2018). "In this study, the dietetic treatment with cranberry was found to beneficially regulate cell proliferation and apoptosis, and meanwhile impede the phosphorylation of EGFR and its downstream Akt in intestinal tumors in Apcmin/+ mice, compared with basal diet." (PMID 29228651, 2017). "Immunostaining supported that phosphorylation of EGFR and Akt in intestinal tumors from distal small intestine were suppressed by cranberry supplementation." (PMID 29228651, 2017). "Another process that relies on EGFR signaling is the development of intestinal tumors, which originate from crypt stem cells." (PMID 29312533, 2017). "Moreover, ZD6474-treated mice had significantly fewer small intestinal tumours, demonstrating the functional requirement of VEGFR, RET, and EGFR activity for the optimal growth of intestinal tumours with activated TGFβ/ALK5 signalling." (PMID 36477656, 2022). "Furthermore, phosphorylation of EGFR and Akt in intestinal tumours was also up‐regulated by DCA treatment." (PMID 29956475, 2018). "Another process that relies on EGFR signaling is the development of intestinal tumors." (PMID 29312533, 2017). "We analyzed the activation of EGFR signaling pathway in intestinal tumors of Apcmin/+ mice." (PMID 24279644, 2013). "Therefore, the requirement for the ERBB3 signaling pathway in intestinal tumor progression could result from its unique role of linking EGFR signaling to PI3K/AKT, thus activating the PI3K pathway to promote cell proliferation." (PMID 34843459, 2021). "Furthermore, immunostaining analysis in Apcmin/+ mice also suggested that releasing of AREG could activate EGFR/Akt pathway to further promote intestinal tumour development after DCA treatment." (PMID 29956475, 2018). "Therefore, we hypothesize that berberine inhibits intestinal tumor development in Apcmin/+ mice through concomitant suppression of EGFR pathway, leading to decreasing tumor cell proliferation and increasing apoptosis." (PMID 24279644, 2013). "Western blot analysis and immunostaining were performed to detect the activation of Wnt and epidermal growth factor receptor (EGFR) signaling pathways and COX-2 expression in the intestinal tumor cells." (PMID 24279644, 2013). "For example, an ERBB2-amplified intestinal tumor-like organoid exhibited significant responsiveness to the dual ERBB2/EGFR inhibitor lapatinib, but not to a strain with an epidermal growth factor receptor-amplified status with a normal ERBB2 allele." (PMID 38496762, 2024).
intestinal tumor (continued). "ADAM‐17/EGFR signalling axis was also activated in intestinal tumours of DCA‐treated Apcmin/+ mice, whereas no significant change occurred in tumour adjacent tissues after DCA exposure." (PMID 29956475, 2018). "Furthermore, berberine decreased the activation levels of Wnt and EGFR signaling pathways, and down-regulated COX-2 expression in intestinal tumor cells and prostaglandin E2 production in the small intestine." (PMID 24279644, 2013). "Furthermore, phosphorylation of EGFR, ERK, and Akt in intestinal tumors was suppressed by berberine treatment." (PMID 24279644, 2013). "We found that DCA could activate epidermal growth factor receptor (EGFR) and promote the release of EGFR ligand amphiregulin (AREG), but not HB‐EGF or TGF‐α in intestinal tumour cells." (PMID 29956475, 2018).